Y_RNA (Y RNA )
Gene: Miscellaneous RNA gene on chromosome 1 (185,634,073 to 185,634,182, reverse strand). Ensembl gene ENSG00000201596.
Homologues: Orthologues: chimpanzee Y_RNA (97% identical), guinea pig Y_RNA (85% identical). Paralogues in human: RNY1 (88% identical), Y_RNA (86% identical), Y_RNA (85% identical), RNY1P10 (84% identical), RNY1P11 (84% identical), Y_RNA (84% identical), Y_RNA (83% identical), Y_RNA (82% identical), RNY1P8 (81% identical), Y_RNA (81% identical), Y_RNA (80% identical), RNY1P7 (79% identical), and 97 more.